IL22 (interleukin 22)
Diseases named in the same sentence as IL22 in open-access papers (continued):
Sharing a sentence is not in itself a finding about the gene and the disease.
gastritis (5 papers, 2016 to 2024). Inflammation of the stomach. "In our study, IL-22 had a significant increase in mild (P = 0.002) and moderate (P < 0.001) gastritis compared with the Hp- group." (PMID 39807418, 2024). "Among the inflammatory cytokines evaluated in this study, IL-17A, IL-17F, and IL-22 can play a crucial role in developing gastritis, especially moderate gastritis, in infected patients with H. pylori." (PMID 39807418, 2024). "We, and others, have shown that IL-22 expression correlates with increased gastritis in the H. pylori-infected humans and H. pylori-infected mice." (PMID 26867135, 2016). "Since IL-22 works with IL-17A to stimulate the strongest antimicrobial response in gastric epithelial cells of humans and of mice, the importance of IL-22 alone was investigated in a mouse model of gastritis." (PMID 26867135, 2016). "Compared to the healthy individuals, the levels of ILC3s and IL22 were observed to be significantly increased in gastritis, and precancerous lesion patients, suggesting that ILC3s may also be associated with gastritis and gastric cancer." (PMID 39309440, 2024). "While these data suggest that Th17 cytokines may enhance expression of antimicrobials and help control H. pylori infection, IL-22 deficiency alone did not alter control of H. pylori colonization and gastritis in the mouse model." (PMID 26867135, 2016). "The levels of IL-2, IL-17A, IL-17F, IL-22, TNF-α, and IFN-γ were significantly higher in patients with mild and moderate gastritis than Hp- group (P≤0.05)." (PMID 39807418, 2024). "The amounts of IL-2, IL-4, IL-17A, IL-17F, IL-22, TNF-α, and TFN-γ were significantly different in patients with gastritis compared with Hp- subjects." (PMID 39807418, 2024). "Accordingly, IL-2, IL-17-A, IL-17F, IL-22, TNF-α, and IFN-γ showed significant increases in patients with mild and moderate gastritis compared with the Hp- subjects." (PMID 39807418, 2024). "Finally, our data suggest that IL-22 is not required for the pro-inflammatory gastritis response to H. pylori infection." (PMID 26867135, 2016). "However, some other studies reported no increase in IL-22 among patients with gastritis." (PMID 39807418, 2024).
glioblastoma (5 papers, 2015 to 2026). The most malignant astrocytic tumor (WHO grade IV). "A previous study showed that IL-22R was activated by IL-22 produced in the microenvironment of human glioblastoma cells, and extends the survival times of cells." (PMID 31391457, 2019). "Consistent with this, human glioblastoma cell lines exposed to IL-22 show increases in both STAT3 and Akt phosphorylation." (PMID 30542269, 2018). "As reviewed elsewhere, IL-22 appears to contribute to host defense at peripheral sites, while in the brain IL-22 can function as a cell survival factor as it protects glioblastoma cells from the apoptosis-inducing effects of serum starvation and Fas ligand exposure." (PMID 30542269, 2018). "The expression of IL22 was low in glioblastoma and normal tissues, whereas IL22RA1 was increased in primary and recurrent glioblastomas compared with normal tissues." (PMID 35874683, 2022).
Hyperkeratosis (5 papers, 2014 to 2024). Hyperkeratosis is a histopathological term defining a thickened stratum corneum and may be present in many different skin conditions, with many possible overlaps. "Compared with control mice, mice treated with solenopsin analogues for 28 days showed significant decreases in acanthosis and hyperkeratosis, decreases in TLR4 expression and IL-22, and increases in IL-12." (PMID 39766206, 2024).
kidney injury (5 papers, 2017 to 2021). Trauma to the kidney. "Second, IL-22 has been reported to have both beneficial and detrimental effects depending on the type of experimental model of kidney injury." (PMID 28143481, 2017). "The cytokine IL-22 is a member of the IL-10 family and can directly stimulate TEC regeneration following kidney injury." (PMID 34234783, 2021).
leprosy (5 papers, 2013 to 2026). Leprosy is a chronic infectious disease affecting primarily the skin and peripheral nervous system. "Within the leprosy spectrum the more resistant paucibacillary form of tuberculoid leprosy had higher IL-17 associated cytokines IL-21, IL-22 and the transcription factor RORC." (PMID 23936569, 2013). "Both types of patients with reactional leprosy demonstrated a rise in IL-17A, IL-17F, and IL-22 levels." (PMID 37809252, 2023). "Among the cytokines that compose the response profile of the cell, IL-22 has been particularly highlighted in leprosy owing to the fact that in the lepromatous form, this cytokine participates in the mechanisms of maturation of the phagolysosome." (PMID 29234318, 2017). "Early reports on leprosy showed increased expression levels of IL-22, IL-13, and FGF b in the lepromatous form, whereas an increase of TNF-α was more evident in the tuberculoid form." (PMID 29234318, 2017). "Moreover, within the leprosy groups IL-21(p<0.002) and IL-22 (p<0.002) were significantly higher in BT as compared to LL type." (PMID 23936569, 2013). "Although there were differences in production of IL-22, TNF-α and IFN-γ between lesions of TT leprosy and healthy controls, skin dermal γδ T cells mainly produced large amount of IL-17A." (PMID 36389696, 2022). "They concluded that leprosy has inadequate secretion of IL-17 but IL-22 was not affected." (PMID 37809252, 2023).
leukemia (5 papers, 2015 to 2022). A malignant (clonal) hematologic disorder, involving hematopoietic stem cells and characterized by the presence of primitive or atypical myeloid or lymphoid cells in the bone marrow and the blood. "17-21 In this review, we discuss the frequency and role of Th22 cell and its important cytokine, IL-22, in leukemia." (PMID 26261700, 2015). "NK-22, a human NK cell subset, secretes leukemia inhibitory factors (LIFs), IL-22, and IL-26." (PMID 32290250, 2020). "Even though the primary role of immune cells, especially Th cells, is the production of IL-22, it is well-known that several immune cells can induce IL-22R1 under certain pathologic conditions such as mycobacterium infected macrophages and leukemia." (PMID 31817755, 2019). "However, the precise roles of Th22 cells in the pathophysiology of specific types of leukemia remain unclear and further studies are required for clarifying the accurate role of Th22 and IL-22 in each type of this disorder." (PMID 26261700, 2015). "Moreover, it showed a strong inhibitory effect on the expression of several proinflammatory cytokines (IL-8, interleukin 12 (IL-12), interleukin 17 (IL-17), interleukin 22 (IL-22), and interleukin 23 (IL-23)) in vitro, in LPS-stimulated human THP-1 leukemia monocytes." (PMID 36615843, 2022).
multiple myeloma (5 papers, 2012 to 2025). "Bone marrow stroma-derived IL-8 and T lymphocyte-derived IL-22 induce CD155 expression in multiple myeloma and hepatocarcinoma, respectively." (PMID 39596207, 2024). "Circulating Th17 cells as well as serum levels of IL-22 and IL-17 are elevated in multiple myeloma patients compared to healthy controls, which has spurred investigations into the role of IL-22 in this disease." (PMID 33692792, 2021). "Recently, IL-22 was found to promote tumor growth in multiple myeloma and mantle cell lymphoma through the aberrant expression of the IL-22 receptor A145,46." (PMID 32973297, 2020). "IL-22 has been involved in the pathophysiology of some malignant diseases, such as multiple myeloma." (PMID 23236476, 2012). "In both HCC and multiple myeloma, IL-22 appears to play a potential role in disease progression." (PMID 40806452, 2025). "Similarly, in multiple myeloma, elevated IL-22 levels are observed during active disease and decline following remission." (PMID 40806452, 2025). "The authors suggest that the elevated circulating IL-22 and IL-17 in multiple myeloma patients may dampen Th1 responses potentially contributing to the observed immune dysfunction in this patient group." (PMID 33692792, 2021). "Recently, it has been reported that in multiple myeloma and hepatocellular carcinoma, CD155 expression is induced by IL-8, activating NF-κB signaling, and IL-22 activates STAT3, respectively." (PMID 39596207, 2024). "IL-22 acts on bone marrow stromal cells (BMSCs), which express IL-22RA1, leading to enhanced secretion of pro-survival and growth-promoting factors, such as IL-6 and VEGF, that support myeloma cell proliferation and survival." (PMID 40806452, 2025).
nasal polyps (5 papers, 2017 to 2025). "IL-22 and its receptor, IL-22R1, are both expressed in nasal polyps, mainly in inflammatory and epithelial cells, respectively." (PMID 41295249, 2025). "IL-22 and IL-22R1 are mainly expressed in infiltrating inflammatory cells and epithelial cells, respectively, in nasal polyps." (PMID 36003393, 2022). "SEB-induced IL-22 production from nasal polyp cells significantly and negatively correlated with the degree of local eosinophilia and the postoperative CT score, and it positively correlated with the forced expiratory volume in 1 s (FEV1)/forced vital capacity (FVC) ratio." (PMID 36003393, 2022). "Cluster 1 (type-3) and 2 (type-1) were associated with a low prevalence of nasal polyps, Cluster 3 (type-1, -2, -3) and Cluster 4 (type-2, -3, medium IL-22) with medium, and Cluster 5 (type-2, -3, high Il-22) and Cluster 6 (type-2) with high prevalence of nasal polyps." (PMID 35455762, 2022). "In Asian patients with CRS, the expression of IL-22 is associated with IL-17A and TNFα and the absence of nasal polyps." (PMID 35455762, 2022). "IL-22 may significantly increase MUC1 mRNA expression in nasal polyp dispersive cells." (PMID 36003393, 2022). "In vitro studies have demonstrated that stimulation with Staphylococcus aureus exotoxins induces IL-22 production, which in turn significantly enhances MUC1 mRNA expression in nasal polyp cells." (PMID 41295249, 2025). "Therefore, IL-22 may reverse the corticosteroid resistance of some difficult-to-treat nasal polyps." (PMID 36003393, 2022). "In the present study with Caucasian patients, we have not observed nasal polyps in Cluster-2 with a negligible concentration of IL-22 and type-1 neutrophilic inflammation." (PMID 35455762, 2022). "In agreement with that finding, we have observed a positive correlation between very low IL-22 and low IL-5 with the absence of nasal polyps in Cluster-2." (PMID 35455762, 2022). "In contrast, an inflammatory role of IL-22 was described in CRS, indicating that IL-22/IL-22Ra1 axis promotes thymic stromal lymphopoietin (TSLP) production under a type-2 microenvironment in airway epithelial cells, potentially contributing to the development of nasal polyps." (PMID 35455762, 2022). "However, in Cluster-6, only three of sixteen patients (19%) had no nasal polyps, despite a marginal concentration of IL-22." (PMID 35455762, 2022). "Here we sought to quantify IL-17A, IL-17F, IL-21, and IL-22 cytokines produced by Th17 cells in mucosal tissue and peripheral blood of CRSwNP, CRS without nasal polyps (CRSsNP) and control patients." (PMID 29311948, 2017).
Nephropathy (5 papers, 2015 to 2022). A nonspecific term referring to disease or damage of the kidneys. "In conclusion, we demonstrated the therapeutic potential and underlying mechanisms of IL‐22 in kidney damage." (PMID 33634980, 2021). "In this study, we indicated that administration of IL-22 markedly attenuated renal tubular injury and function loss in AA-induced nephropathy." (PMID 31616439, 2019). "Therefore, the proposed therapeutic strategies targeting Th17 cells, and the corresponding cytokine IL-22 may have promising applications for the treatment of vasculitis-associated nephropathy." (PMID 35432360, 2022). "Renal index was also drastically increased in AA-induced nephropathy but significantly decreased by IL-22 intervention." (PMID 31616439, 2019). "In summary, we found that the activation of NLRP3 inflammasome participated in the development and progression of AA-induced nephropathy and IL-22 exerted a nephroprotective effect by suppressing renal NLRP3 inflammasome activation." (PMID 31616439, 2019). "In contrast, serum murine IL-1β and IL-8 levels were remarkably downregulated in AAN after IL-22 intervention, suggesting systemic anti-inflammatory effects of IL-22 in AA-induced nephropathy." (PMID 31616439, 2019). "In parallel, semi-quantitative immunoblot analysis also showed significant decreased protein expression of fibronectin, collagen IV, vimentin, and α-SMA in mice with established nephropathy after IL-22 gene therapy." (PMID 28726774, 2017). "Congruent with histological analysis, elevated serum levels of ALT and AST were significantly decreased in mice with established nephropathy after IL-22 gene therapy." (PMID 28726774, 2017). "The expression of IL-22 was further decreased with the progression of DN, whereas IL-22 gene therapy significantly ameliorated renal injury and mesangial matrix expansion in mice with established nephropathy." (PMID 28726774, 2017). "In addition, urinary NAG, as a marker of kidney tubular dysfunction, was obviously downregulated by IL-22 in AA-induced nephropathy." (PMID 31616439, 2019). "Collectively, these data indicated that IL-22 could attenuate renal tubular lesion and fibrosis in AA-induced nephropathy." (PMID 31616439, 2019). "Furthermore, IL-22 largely inhibited renal activation of NLRP3 inflammasome in AA-induced nephropathy." (PMID 31616439, 2019). "In this study, to determine whether intervention by IL-22 could exert similar effects on AA-induced nephropathy, IL-22 was administrated intraperitoneally once a day before each AA exposure for 5 consecutive days." (PMID 31616439, 2019). "Interestingly, IL-22 gene transfer in mice with established nephropathy significantly reduced both blood glucose and urine glucose levels, suggesting better glycemic control in diabetic mice by upregulation of IL-22." (PMID 28726774, 2017). "Understanding the molecular basis of IL‐22 is significant both for exploring how IL‐22 acts to inhibit AKI or ESTD and for discovering molecular modifiers as well as crucial processes involved in preventing kidney damage." (PMID 33634980, 2021). "In addition, IL-22 gene therapy could prevent death of mice with established nephropathy." (PMID 28726774, 2017). "Meanwhile, renal IL-22 expression in AA-induced nephropathy was slightly but not significantly downregulated, indicating possible downregulation of IL-22 in AAN." (PMID 31616439, 2019).
oral candidiasis (5 papers, 2014 to 2024). Infection of the mucosal lining of the mouth with the fungus Candida albicans. "Likewise, mice deficient in IL-22 were slightly susceptible to oropharyngeal candidiasis, indicating a role of IL-22 against oral candidiasis." (PMID 33042126, 2020). "We also tested the effects of IL-22, which was reported to protect epithelia during oral candidiasis in vivo." (PMID 34986345, 2022).
ovarian carcinoma (5 papers, 2019 to 2024). A malignant neoplasm originating from the surface ovarian epithelium. "We recently established the role of Limosilactobacillus reuteri in releasing IL-22 (LR-IL-22) as an effective radiation mitigator, and we have now assessed its effect in an ovarian cancer mouse model." (PMID 38339228, 2024). "Previously, we established that a second-generation probiotic expressing interleukin-22 (LR-IL-22) is a radiation mitigator, and now, we have assessed its effect in an ovarian cancer mouse model." (PMID 38339228, 2024). "The results of Il-22 concentration measurement in the serum and peritoneal fluid of women with ovarian cancer were presented in the form of the median and the lower and upper interquartile range (Q1 and Q3)." (PMID 34300224, 2021). "Modulation in the IL-21 and IL-22 system may affect the course of the inflammatory process that accompanies the development of cancer, which may prove useful in the development of new diagnostic and therapeutic strategies used in patients with ovarian cancer, which requires further studies." (PMID 34300224, 2021). "According to the authors, IL-22 is a potential therapeutic target and/or biomarker in human ovarian cancer." (PMID 34300224, 2021). "Recent studies have shown that interleukin 21 and interleukin 22 play an important role in the pathogenesis of cancer, which role in the formation and development of ovarian cancer is still not fully understood." (PMID 34300224, 2021). "Further analysis included the evaluation of interleukin 22 expression at the mRNA level in tumor tissue and serum and peritoneal fluid concentration in women with ovarian cancer." (PMID 34300224, 2021). "Then, the concentration of IL-22 in serum and peritoneal fluid in women with ovarian cancer depending on the degree of histopathological differentiation of the cancer was analyzed." (PMID 34300224, 2021). "The concentration of IL-21 and IL-22 in the serum and in the peritoneal fluid of women with ovarian cancer varied depending on the degree of histopathological differentiation of the cancer and showed statistical variability compared to controls." (PMID 34300224, 2021). "The analyses conducted so far on the evaluation of IL-21 and IL-22 in ovarian cancer have been interesting and induce further research." (PMID 34300224, 2021). "In human ovarian cancer, IL-22-producing ILC3s prevent tumor-infiltrating lymphocyte activation and proliferation, whereas the release of IL-22 and IL-17 by ILC3s modulates intestinal immune pathology." (PMID 32117199, 2019). "In a mouse model of WAI in ovarian cancer, we reported that the oral administration (gavage) of a second-generation probiotic L. reuteri (LR) that was engineered to synthesize interleukin-22 (LR-IL-22) is a safe and effective intestinal radioprotector." (PMID 36980556, 2023). "Interleukin-22 has been shown to be an important factor in the ovarian cancer tumor microenvironment and may find application as a potential therapeutic target and/or biomarker." (PMID 34300224, 2021). "Studies have shown that interleukin-22 is an important factor in the ovarian cancer tumor microenvironment because it stimulates tumor growth by increasing proliferation and serves as a protective factor for ovarian cancer during TNF-induced apoptosis." (PMID 34300224, 2021). "A statistically significant higher concentration of IL-22 in the serum of women with ovarian cancer was demonstrated compared to the concentration in the control group (p < 0.001), where Q1 and Q3 were respectively: 66.01 and 140.04 with a median of 98.62 pg/mL." (PMID 34300224, 2021). "In addition, a statistically significant higher concentration of the parameter in the serum of women with ovarian cancer was demonstrated compared to the concentration in the peritoneal fluid, which indicates increased secretion of Il-22 in the systemic immune response." (PMID 34300224, 2021).
ovarian carcinoma (continued). "Local and systemic changes in the immune system with the participation of soluble mediators IL-21 and IL-22 indicate the participation of these parameters in the development of ovarian cancer and may participate in pro and anti-inflammatory activation involving the tested cytokines." (PMID 34300224, 2021).